EGFR (epidermal growth factor receptor)
Diseases named in the same sentence as EGFR in open-access papers (continued):
Sharing a sentence is not in itself a finding about the gene and the disease.
lung cancer (continued). "Potentiation of EGFR action by MET in lung cancer has been found to be independent of HGF leading to speculation in favor of an intracellular lateral signaling cascade." (PMID 29348142, 2018). "Furthermore, this mechanism of resistance is not unique to lung cancer as an EMT mechanism of resistance to EGFR inhibition has been observed in HNSCC cell lines." (PMID 29458371, 2018). "We found that EHD1 was an important factor in EGFR-TKI resistance and the cancer stem-like cell phenotype of lung cancer, and these results suggest that targeting the NF-κB/miR-590/EHD1 pathway has potential therapeutic promise in EGFR-mutant NSCLC patients with acquired EGFR-TKI resistance." (PMID 29549343, 2018). "Moreover, in lung cancer, another aggressive neoplasm, METTL3 was shown to act as an oncogene, inducing tumor growth and proliferation, also promoting translation of important genes such as epidermal growth factor receptor (EGFR) and tafazzin (TAZ)." (PMID 30428628, 2018). "Also, the ERK1 checkpoint in the downstream of EGFR and IGF1R is inactivated by miR-140-3p, leading to a reduction of active AP-1 proteins including FOS and c-JUN, thus modulate invasion and transformation of lung cancer cells." (PMID 30559931, 2018). "Using RNAi, the authors showed that Fas could render EGFR mutant lung cancer cells independent of the mutant EGFR and thereby resistant to erlotinib by acting upstream of persistent NFkB signaling and an unidentified MEK-independent pathway." (PMID 30127519, 2018). "Our current results thus suggest the possible future use of NUFS‐sErt to manage CNS metastases in EGFR‐mutant lung cancer patients, particularly in cases that are not responsive to osimertinib or experience progression after an initial response to radiotherapy." (PMID 30350450, 2018). "Although C1GALT1 controls many cellular behaviors and EGFR serves as a therapeutic target in several malignancies, including HNSCC, lung cancers, and colon cancers, the therapeutic potential of targeting C1GALT1 and its effect on EGFR signaling in HNSCC remain unclear." (PMID 29930379, 2018). "EGFR activates miR-7 through the Ras/extracellular signal-regulated kinase (ERK)/Myc pathway and inhibits ETS2 repressor factor (ERF, a transcriptional repressor of V-ets avian erythroblastosis virus E26 oncogene homolog 2 (Ets2)), thereby promoting cell growth and the occurrence of lung cancers." (PMID 30400981, 2018). "Next, we examined the relative levels of EGFR to control β-actin expression and miR-370 to U6 transcripts in human lung cancer A549, H460, H157, XWLC-05 cells, and non-tumor bronchial epithelial Beas-2b cells by Western blot and quantitative RT-PCR, respectively." (PMID 29152147, 2017). "We identified seven proteins (Amph, Dok3, Ddx17, Mbip, Rim2, Skap2, TACC3, and Usp33) that are predicted to be EGFR interaction partners and/or share interaction partners within the EGFR pathway, and three of these (Amph, Rim2, and TACC3) show increased expression levels in lung cancer." (PMID 27956147, 2017). "Interestingly, another study in lung cancer also showed that PKM2 could directly interacted with heat-shock protein 90 (HSP90), and thus increase the stability EGFR." (PMID 29262861, 2017). "Combined use of EGFR-TKI and MET inhibitors or inhibition of downstream signaling molecules might be a better second or third line choice for a group of patients with advanced lung cancer harboring wild-type EGFR." (PMID 26919104, 2016). "However, a recent study showed that PTPN3 inhibits lung cancer cell proliferation and migration by promoting the endocytic degradation of EGFR, indicating that PTPN3 may act as a tumour suppressor in lung cancer through its modulation of EGFR signalling." (PMID 27833130, 2016).
lung cancer (continued). "Additionally, recent studies indicated that in the anti-EGFR therapy, overexpression of LMO1 may be a predictive marker for the colorectal cancer, lung cancer, and prostate cancer." (PMID 27009839, 2016). "Indeed, a previous report showed that suppression of EGFR signaling induced Stat3 activation in EGFR-mutant but not in EGFR wildtype lung cancer cells." (PMID 27419630, 2016). "In our clinic in treating M1a lung cancer patients through intrapleural perfusion with hyperthermic chemotherapy (IPHC) followed by cycles of systemic chemotherapy (we termed this procedure IPHC complete treatment, IPHC-CT), we found dramatic tumor shrinkage in mutant EGFR-positive patients." (PMID 26654941, 2016). "Primary resistance to EGFR-TKI of lung cancer cells is related to EGFR-TKI nonresponders." (PMID 27368002, 2016). "The CD4/CD8 ratio was lower in T cells at resistance in both patients, as it was the case for the mouse EGFR TL and Kras lung cancer models In the anti-PD-1-resistant samples, we noted increased effector memory CD8 T cells (CCR7−CD45RA−) as compared with untreated samples." (PMID 26883990, 2016). "Researchers have found tumor mutational frequencies and spectra differences between smokers and nonsmokers, as indicated by the reported differences in the frequency of somatic mutations of EGFR and KRAS observed between smoking and nonsmoking lung cancer patients." (PMID 27227356, 2016). "Moreover, both IL10 and EGFR enhance lung cancer formation, and IL10 might increase EGFR expression." (PMID 26956044, 2016). "The anti-tumor effect of WJ was abolished in Y1045F-mutant EGFR A549-Luc orthotopic lung tumors and WJ induced-EGFR degradation in wild-type EGFR A549 tumors was not seen in Y1045F-mutant EGFR A549 tumors, indicating the critical role of EGFR in lung cancer formation." (PMID 25980579, 2015). "The EGFR translocation in mitochondria could also be observed in other lung cancer cells regardless of their EGFR genotypes." (PMID 26497368, 2015). "Albeit within a relatively small number of lung cancer samples, gene amplification and overexpression of MAPK7 appeared to be a distinct molecular feature, as of the 3 samples, only 1 contained an EGFR L858R mutation and none had KRas mutation (data not shown)." (PMID 26040563, 2015). "To further investigate the impact of ERβ localization on EGFR-TKI efficacy, we analyzed correlations between ERβ localization (cytoplasmic and/or nuclear) and survival after EGFR-TKI therapy in 184 Chinese patients with advanced NSCLC and confirmed the clinical results in lung cancer cell lines." (PMID 26096604, 2015). "Thus, finding a new agent against EGFR wild-type and TKI-resistant lung cancers is a necessity." (PMID 25955608, 2015). "With a better understanding of the biology of lung cancer in recent years, several groups have proposed novel strategies targeting the epidermal growth factor receptor (EGFR), other receptor and non-receptor tyrosine kinases, and vascular endothelial growth factor (VEGF) pathways." (PMID 26681199, 2015). "Functional and mechanistic studies have indicated that TERT plays an important role in regulating oncogenic signaling pathways and acts as a transcriptional regulator of EGFR expression, implying its potential role in the progression of lung cancers arising in never smokers." (PMID 26020272, 2015). "The emerging role of miRNAs in regulation the EGFR signaling pathway and therapeutic responses to EGFR-TKIs has provided a new avenue for developing novel agents and approaches to resensitize TKI resistance and improve the overall clinical outcomes of TKI-treatment in patients with lung cancer." (PMID 26273639, 2015). "Moreover, it has been reported that PI3K-mTOR inhibition does not promote substantial apoptosis in the EGFR mutant lung cancer while it induced apoptosis in HER2-amplified breast cancer." (PMID 24337632, 2014).
lung cancer (continued). "Clinical trials investigating EGFR inhibitors revealed that responses occurred in a selective fraction of lung cancer patients, preferentially in never-smokers diagnosed with activating mutations in the EGFR gene and a adenocarcinoma or bronchioalveolar histotype." (PMID 24551227, 2014). "Interestingly, KPT-185 equally inhibited the viability of EGFR-TKI-resistant H1975 and H1650GR cells and EGFR-TKI-sensitive HCC827 cells, indicating that KPT-185 may be a good candidate for the effective control of EGFR-TKI-resistant lung cancers." (PMID 24595136, 2014). "Although we confirmed meaningful EGFR endocytosis clues that could contribute to treating lung cancer without appropriate therapeutic options, this study had some limitations." (PMID 24658031, 2014). "Although many lines of evidence suggest that EGFR mutations are more common among women, never-smokers, patients with adenocarcinoma-type lung cancer, and patients of East Asian ethnicity including Japanese, the association of COPD prevalence with EGFR mutations has not been fully evaluated." (PMID 24498965, 2014). "Last, advanced stage ALK-positive lung cancers may have a higher propensity for pleural and pericardial disease than lung cancers lacking ALK, KRAS, or EGFR mutations." (PMID 24955213, 2014). "Notably, SRSF2 over-expression modified HER1/EGFR and VEGFA expression in H358 lung cancer cells." (PMID 24428911, 2014). "Furthermore, acquired cisplatin resistance in EGFR-expressing lung cancer cells did not affect the sensitivity to EGFR tyrosine kinase inhibitors." (PMID 25216514, 2014). "Our study demonstrated that EGFR expression is regulated by RBM5 in lung adenocarcinomas cells either in a direct or indirect way, which might be meaningful with regards to target therapy in lung cancer." (PMID 25441176, 2014). "Rescue or maintenance EGFR TKIs can induce apoptosis of lung cancer cells and may favor MV weaning for critical non-squamous NSCLC patients." (PMID 25050082, 2014). "ERBB3 bound EGFR, while we could not identify any ERBB2 peptides, suggesting that EGFR may be the primary partner of ERBB3 in these lung cancer cells with activating EGFR mutations." (PMID 24189400, 2013). "To determine which of these 14 core network proteins are specifically involved in mutant EGFR-dependent survival as opposed to survival across wild-type EGFR lung cancer cell lines, we examined a larger battery of lung cancer cell lines for changes in viability following siRNA treatment." (PMID 24189400, 2013). "Cell line experiments have also shown that both EGFR and MET activation and the interaction between the corresponding signaling pathways may mediate crizotinib resistance, suggesting that both signaling by EGFR and MET may be crucial for the survival of lung cancer cells upon ALK inhibition." (PMID 24279718, 2013). "However, a model of acquired resistance to gefitinib in EGFR mutant lung cancer cells has not been developed to date, despite the fact that the acquisition of EGFR-TKI resistance in NSCLC patients with EGFR mutations underscores its clinical relevance." (PMID 24339922, 2013). "However, a model of acquired resistance to gefitinib has not been developed in EGFR mutant lung cancer cells, which is of clinical importance." (PMID 24339922, 2013). "To determine the differential phosphorylation status of EGFR phosphorylation sites, we detected EGFR phosphorylation at different sites in H1299 lung cancer cells that stably expressed an empty vector, EGFR-WT or EGFR-L858R mutant with or without ligand stimulation." (PMID 23520446, 2013). "Erlotinib-resistant, EGFR wild-type lung cancers do not exhibit this effect." (PMID 24100924, 2013). "Despite being the activator of RAS signalling pathway, EGFR derives less attention in this aspect due to activating mutations in KRAS, which are significantly associated with lack of response or resistance with some of the EGFR inhibitors like cetuximab in colorectal and lung cancers." (PMID 24147022, 2013).
lung cancer (continued). "In our previous Japanese cohort study of patients with EGFR mutant lung cancer, high HGF expression was detected in 61% of tumors with acquired resistance and in 29% of tumors with intrinsic resistance to EGFR-TKIs, suggesting that targeting HGF may overcome resistance to EGFR-TKIs." (PMID 24386407, 2013). "However, in contrast to the lung cancer models, breast cancers are not initially sensitive to EGFR TKIs and therefore do not develop an acquired resistance in response to Met upregulation." (PMID 22788954, 2012). "Recent studies of Asian and Western patients have firmly established that lipoprotein receptor-related protein-1, ribonucleotide reductase M1 (RRM-1), EGFR, and excision repair cross-complementing gene 1 (ERCC-1) may be useful molecular markers to guide drug selection in patients with lung cancer." (PMID 22890830, 2012). "Importantly, IκB status was not predictive of outcomes in EGFR mutant lung cancer patients treated with surgery or chemotherapy, indicating NFκB signaling is specific biomarker of EGFR TKI response in this patient population." (PMID 22970367, 2012). "EGFR mutant lung cancers with genetic alterations that activate the PI3K-AKT signaling pathway or IGF1R signaling may benefit from treatment with PI3K or AKT inhibitors or an IGF1R antibody, respectively, in combination with an EGFR TKI." (PMID 22970367, 2012). "Moreover, immunoprecipitation analysis revealed that each of these RTKs formed a heterodimer with MET, demonstrating for the first time that EGFR, HER2, HER3, and RET are the main heterodimerisation partners of MET in MET amplification-positive lung cancer cells." (PMID 21847121, 2011). "Our data suggest that heterodimers of MET with EGFR, HER2, HER3, or RET have differential roles in tumour development, and they provide new insight into the function of trans-phosphorylated RTKs as heterodimerisation partners of MET in lung cancer with MET amplification." (PMID 21847121, 2011). "Specifically, a fold change of 1.76 over-expression of EGFR (210984_x_at) was observed in Erlotinib resistant vs. sensitive lung cancer cell lines (P<0.05), whereas no significant differential expression of EGFR was observed in other studies drugs (results not shown)." (PMID 20808922, 2010). "However mutant EGFR does not drive the entire tyrosine phosphorylation pattern in lung cancer, as cells with mutant EGFR can form distinct clusters." (PMID 20976048, 2010). "Overexpression of EGFR and COX-2 may play an important role in the tumorgenesis, progression and malignancy of lung cancer.Detection of EGFR and COX-2 expression might be helpful to diagnosis and prognosis of lung cancer." (PMID 20673501, 2010). "By identifying the EGFR 15/18 bp deletions in blood, the ultra high analytical selectivity of MAP could potentially be applied to early lung cancer detection or possibly facilitate more rational chemotherapy delivery by monitoring the efficacy of therapy or predicting recurrence." (PMID 19789704, 2009). "Despite broad enthusiasm regarding the potential value of EGFR target modulation in cancer therapy, the field rests at an important crossroads in light of negative results from several large-scale phase III clinical trials in lung cancer reported during 2002–2003." (PMID 18519000, 2008). "As has been described, EGFR-TKIs are not universally effective for lung cancer, but these drugs are effective in patients who have particular clinical or biological characteristics, for example, Asian, nonsmoking female patients with adenocarcinomas with EGFR mutations." (PMID 17325698, 2007). "Across the entire cohort of 23 lung cancer cell lines, those showing sensitivity to gefitinib exhibited greater phosphorylation of Akt and EGFR without ligand stimulation than gefitinib-resistant cell lines, according to the Mann-Whitney test (P = 0.0016, P = 0.0274, respectively)." (PMID 17150102, 2006).
lung cancer (continued). "In addition to traditional surgical treatment and chemotherapy, targeted therapies represented by EGFR inhibitors, ALK inhibitors, ROS1 inhibitors and immunotherapies represented by PD‐1/PD‐L1 inhibitors and CTLA‐4 inhibitors are playing an increasingly critical role in the treatment of lung cancer." (PMID 40845073, 2025). "However, the endocytosis mechanism of EGFR in lung cancer is not yet known." (PMID 39910656, 2025). "GM‐protac could induce EGFR degradation under a lower concentration compared to G‐protac, and inhibit HDAC enzyme activity by increasing the acetylation of HDAC substrate histone 3 in osimertinib or almonertinib resistance lung cancer cells H1975‐OR or H1975‐AR cells." (PMID 40842076, 2025). "Although the frequency of both occurring simultaneously in patients with lung cancer is very low, targeting both EGFR and NTRK fusions together may provide clinical benefits, making them a treatment option for patients who have developed resistance to EGFR-TKIs." (PMID 41383499, 2025). "Secondly, as a reduction in EGFR expression as a result of melittin treatment has never been reported in lung cancer cells, this could be because EGFR in lung cancer cells is highly expressed, potentially leading to a reduced sensitivity to melittin-induced effects." (PMID 40141140, 2025). "Notably, epithelial–mesenchymal transition (EMT) transcription factors such as ZEB1, Slug, and TWIST1 have been identified as drivers of EGFR TKI resistance mediated by EMT, suggesting that these transcription factors could be potential targets for treating EMT-related resistance in lung cancer." (PMID 40304000, 2025). "The LUNGevity report on experiences of patients with lung cancer in the US with biomarker testing also highlighted challenges with interpreting the results of biomarker testing, as captured in a participant’s quote, “in my report...genetic findings, EGFR exon 19 deletion, no problem." (PMID 39217303, 2024). "However, the EGFR-TKIs used for early-stage lung cancer is not routinely." (PMID 38528507, 2024). "Furthermore, DRD1 modulates the expression of EGFR and PD‐L1, two molecules that are key drug targets of FDA‐approved and development‐stage therapies in lung cancer and other cancer types, so targeting DRD1 signaling may also be able to augment these therapies." (PMID 38572507, 2024). "However, there was no research focus on stage I lung cancer, and these early stage patients will not receive any treatment after surgery, whether the primary EGFR T790M will be an unfavorable prognostic marker need further investigation." (PMID 38348924, 2024). "In addition to the importance of EGFR at late stages of disease, the activity of ERBB receptors is critical during the early stages of KRAS-driven lung tumours, with the addition of tyrosine kinase inhibitors to MEK inhibition improving survival of a KRas driven murine lung cancer model." (PMID 38434478, 2024). "We reasoned that YY1 function might not be restricted to EGFR-mutant lung cancer." (PMID 39604408, 2024). "A previous preclinical study revealed that oncogenic EGFR mutations play an important role in creating a non-inflamed tumor microenvironment (TME) and that the expression of PD-L1 in cancer cells do not reproducibly predict the efficacy of ICI in EGFR-mutant lung cancer." (PMID 38347279, 2024). "In the present study, we also found that EGFR was up-regulated after reducing miR-545-3p abundance in LUAD cell lines, which revealed competitive endogenous RNA (ceRNA) mechanisms controlling EGFR may be a potential complementary strategy for lung cancer treatment." (PMID 36787056, 2023).